GID8 (GID complex subunit 8 homolog)
Description:
Core component of the CTLH E3 ubiquitin-protein ligase complex that selectively accepts ubiquitin from UBE2H and mediates ubiquitination and subsequent proteasomal degradation of the transcription factor HBP1. Acts as a positive regulator of Wnt signaling pathway by promoting beta-catenin (CTNNB1) nuclear accumulation.
Synonyms: Twa1; C20orf11; FLJ20602; bA305P22.1
Tractability: PROTAC: UniProt records ubiquitination sites on it; ubiquitination databases record sites on it; its protein half-life has been measured.
Gene: Protein-coding gene on chromosome 20 (62,937,060 to 62,948,589, forward strand). Ensembl gene ENSG00000101193.
Subcellular location: Cytoplasm; Nucleus
Subcellular location (Human Protein Atlas): Nucleoplasm; Cell Junctions
Pathways (Reactome):
Metabolism: Regulation of pyruvate metabolism
Gene Ontology:
Molecular function: protein binding; protein-macromolecule adaptor activity; protein homodimerization activity
Biological process: positive regulation of canonical Wnt signaling pathway; positive regulation of cell population proliferation; proteasome-mediated ubiquitin-dependent protein catabolic process
Cellular component: cell junction; cytoplasm; cytosol; nucleoplasm; nucleus; ubiquitin ligase complex; GID complex
Genetic constraint (gnomAD): Loss-of-function variants: 6 observed, 20.9 expected, observed/expected ratio (o/e) 0.29, 90% interval 0.16 to 0.57. The upper end of that interval is the gene's LOEUF score, 0.57, which puts it in group 2 of 6, group 1 being the genes least tolerant of losing a copy. Missense variants: 138 observed, 245.92 expected, observed/expected ratio (o/e) 0.56, 90% interval 0.49 to 0.65. Synonymous variants: 94 observed, 96.96 expected, observed/expected ratio (o/e) 0.97, 90% interval 0.82 to 1.15.
Homologues: Orthologues: chimpanzee GID8 (100% identical), macaque GID8 (100% identical), guinea pig GID8 (99% identical), mouse Gid8 (99% identical), rat Gid8 (99% identical), dog GID8 (99% identical), tropical clawed frog gid8 (95% identical), zebrafish gid8b (94% identical), zebrafish gid8a (91% identical), pig GID8 (84% identical), Drosophila melanogaster Hou (58% identical), Caenorhabditis elegans gid-8 (27% identical). Paralogues in human: RANBP10 (29% identical), RANBP9 (29% identical), SPRYD3 (16% identical).
Diseases named in the same sentence as GID8 in open-access papers:
GID8 is named in the same sentence as 8 diseases in open-access papers, as found by Europe PMC text mining. Sharing a sentence is not in itself a finding about the gene and the disease. The quoted sentences say what the papers report.
gastric cancer (3 papers, 2012 to 2022). A primary or metastatic malignant neoplasm involving the stomach. "PSMA7 and GID8 are two genes encoded within 20q13.33 that were described as possible gene targets in gastric cancer." (PMID 36232418, 2022). "High expression of GID8 was associated with a poor prognosis of colorectal and gastric cancers." (PMID 36225588, 2022).
colorectal cancer (1 paper, 2019). A primary or metastatic malignant neoplasm that affects the colon or rectum. "In fact, GID8 was shown to be significantly upregulated in colorectal cancer and its nuclear levels were inversely correlated with prognosis." (PMID 31885576, 2019). "Considering that the hyperactivation of WNT/β-catenin signaling is a major cause of human colorectal cancer and is linked to tumor-initiating cells renewal, these results indicate a major role for GID8 in the pathogenesis of colorectal cancer." (PMID 31885576, 2019).
tumor (4 papers, 2012 to 2025). "Inhibiting GID8 significantly impairs cell proliferation, invasion, and tumor growth in mouse models." (PMID 41020873, 2025). "Highly expressed GID8 maintains the transcription and protein stability of SLC1A3 and GLS, increasing glutamine uptake and catabolism in tumor cells to meet the carbon and energy demands for rapid proliferation and metastasis." (PMID 41020873, 2025).
cancer (1 paper, 2019). A tumor composed of atypical neoplastic, often pleomorphic cells that invade other tissues. "GID8 not only promoted proliferation of colon cancer cells, but its depletion reduced cancer cell growth and expression of WNT-dependent genes." (PMID 31885576, 2019). "In addition, this establishes GID8 as a potential enhancer of WNT signaling in any type of cancer where this pathway is hyperactivated." (PMID 31885576, 2019).
GID8 also shares sentences with these, for which no sentence is quoted: adenocarcinoma (1 paper); colorectal (1); lung carcinoma (1); squamous cell carcinoma (1).